BEX1 (brain expressed X-linked 1)
Diseases named in the same sentence as BEX1 in open-access papers (continued):
Sharing a sentence is not in itself a finding about the gene and the disease.
Hydrocephalus (1 paper, 2022). Hydrocephalus is an active distension of the ventricular system of the brain resulting from inadequate passage of CSF from its point of production within the cerebral ventricles to its point of absorption into the systemic circulation. "Hypoplasia of the cerebellar vermis causing hydrocephalus was observed in Bex1 mutant mice." (PMID 35144600, 2022). "Moreover, Bex1 mutant mice exhibited an increased head circumference due to hydrocephalus accompanied by hypoplasia of the cerebellar vermis." (PMID 35144600, 2022).
injury (1 paper, 2018). Damage inflicted on the body as the direct or indirect result of an external force, with or without disruption of structural continuity. "Taken together, these results indicate that BEX1 is required for LPC expansion and proliferation in the CDE diet-induced liver injury model." (PMID 29907129, 2018).
leukemia (1 paper, 2013). A malignant (clonal) hematologic disorder, involving hematopoietic stem cells and characterized by the presence of primitive or atypical myeloid or lymphoid cells in the bone marrow and the blood. "Interestingly, DHH-RHEBL1-positive patients showed higher expression of several genes known to be associated with leukemia occurrence and/or tumor progression, such as FLT3, BEX1, MUC4 and AFAP1L2." (PMID 24127550, 2013).
leukoplakia (1 paper, 2016). A white patch or plaque on a mucous membrane that cannot be characterized clinically or pathologically as any other disease. "The correlation of low BEX4 expression with poor cancer-free survival in leukoplakia patients was more significant than other BEX family members including BEX1, BEX2, NGFRAP1 (BEX3) and BEX5." (PMID 27297407, 2016).
lung adenocarcinoma (1 paper, 2021). A carcinoma that arises from the lung and is characterized by the presence of malignant glandular epithelial cells. "Conversely, a study provided evidence that the correlated expression of BEX1 and BEX4 is associated with lung adenocarcinoma prognosis." (PMID 34576008, 2021).
neuroblastoma (1 paper, 2017). Neuroblastoma (NB) is the most common solid, extracranial childhood tumor. "Our results from curcumin treated N2a neuroblastoma cells indicated the induction of Bex1, Bex2 and Bex3 genes prior to activation of apoptotic pathways and continued to last for 24 hours post treatment." (PMID 28145533, 2017). "Therefore, induction of Bex genes (especially Bex6, Bex1 and Bex4 genes) functions as tumor suppressors at least in N2a neuroblastoma cells and may serve as an alternative for the treatment of neuroblastomas and other cancers with silenced Bex genes." (PMID 28145533, 2017).
oral squamous cell carcinoma (1 paper, 2015). "It has been shown that BEX1 suppresses NF-κB signaling in oral squamous cell carcinoma." (PMID 26046670, 2015).
ovarian carcinoma (1 paper, 2024). A malignant neoplasm originating from the surface ovarian epithelium. "Subsequently, we discerned an amplified synergistic outcome when Brain Expressed X-linked protein 1 (BEX1) was subject to overexpression in ovarian carcinoma cellular cultures in conjunction with erlotinib administration." (PMID 38264719, 2024). "Additionally, through the overexpression of BEX1 in ovarian cancer cells, partial validation of the utility of the feature selection component has been achieved." (PMID 38264719, 2024).
pulmonary oedema (1 paper, 2017). "Bex1-KO mice also were protected from developing pulmonary oedema with TAC, and they showed reduced cardiac fibrosis compared with WT controls." (PMID 29192139, 2017).
Sepsis (1 paper, 2025). Sepsis is defined as life-threatening organ dysfunction caused by a dysregulated host response to infection. "However, the relative expression levels of BEX1, and EPHX2 were significantly higher in the sepsis group than those in the control group." (PMID 40526611, 2025).
steatosis (1 paper, 2018). Increased lipid within the cytoplasm of cells. "In our experiment, a population of BEX1+ hepatocytes was observed in CDE diet-fed mice, and CDE diet-fed Bex1−/− mice showed more serious macrovesicular steatosis." (PMID 29907129, 2018). "Furthermore, compared with CDE diet-fed WT mice, the livers of CDE diet-fed Bex1−/− mice exhibited more serious macrovesicular steatosis, indicated by more macrovesicular fat droplets and fat accumulation." (PMID 29907129, 2018).
teratocarcinoma (1 paper, 2018). A germ cell tumor characterized by the presence of an embryonal carcinoma component and a teratoma component. "Brain-expressed X-linked 1 (BEX1), an adaptor or modulator of intracellular signalling, was first characterized with reduced expression in F9 teratocarcinoma cells following retinoic acid treatment." (PMID 29907129, 2018).
teratoma (1 paper, 2023). A non-seminomatous germ cell tumor characterized by the presence of various tissues which correspond to the different germinal layers (endoderm, mesoderm, and ectoderm). "BEX1 was initially thought to be associated with retinoic acid differentiation in teratomas." (PMID 37745297, 2023).
triple-negative breast carcinoma (1 paper, 2020). An invasive breast carcinoma which is negative for expression of estrogen receptor (ER), progesterone receptor (PR), and human epidermal growth factor receptor 2 (HER2). "While changes such as the upregulation of ADAM19 in the invading subpopulation may be shared among the triple negative breast cancer cells tested in this study, other genes, such as BEX1 and CDH13, were seen in some samples but not in others." (PMID 32238832, 2020).
viral myocarditis (1 paper, 2022). Myocarditis that is caused by an infection with a viral agent. "Using a murine model of CVB3-induced viral myocarditis, we found that BEX1 expression was reduced one week after infection, suggesting that BEX1 is regulated by viral stress." (PMID 35192678, 2022).
tumor (23 papers, 2008 to 2025). "One interesting find is the high expression of the novel BEX1 gene (brain expressed, X-linked 1) in the NE tumour cell group." (PMID 18827820, 2008). "TRIM26, PTPN6 (a cytoplasmic phosphatase), and BEX1 play critical roles in tumor immune inflammation." (PMID 38814177, 2024). "AML patients positive for FLT3-ITD mutation along with reduced BEX1 expression displayed poor overall survival suggesting that BEX1 acts as a tumor suppressor in AML." (PMID 26046670, 2015). "Since BEX1 is capable of limiting cell proliferation, colony formation, tumor formation and inducing apoptosis, drugs that enhance BEX1 expression would be beneficial for the treatment of patients with loss of BEX1 expression in FLT-ITD driven AML." (PMID 26046670, 2015). "Taken together, our study suggests that BEX1 has a tumor suppressor role in AML and that loss of BEX1 expression results in poor overall survival in FLT3-ITD positive AML patients." (PMID 26046670, 2015). "In conclusion, current studies suggest that BEX1 is expressed in a variety of cells where it acts as a tumor suppressor." (PMID 26046670, 2015). "BEX1 localized to the cytosolic compartments and overexpression of BEX1 resulted in decreased cell proliferation and colony formation, delayed tumor formation and increased apoptosis by inhibiting AKT signaling induced by FLT3-ITD." (PMID 26046670, 2015). "We observed that BEX1 expression significantly reduced tumor volume and tumor weight in Ba/F3 as well as in 32D cells in xenografted mice." (PMID 26046670, 2015). "Our previous study revealed global epigenetic aberrations in smoking-associated OSCC patients, and identified BEX1 and LDOC1 as 2 X-linked tumor suppressor genes with promoter methylated in 75% and 89% of OSCC tumor samples, respectively." (PMID 26317789, 2015). "The observation that BEX1 expression promotes apoptosis and inhibits cell proliferation, colony formation and tumor formation induced by FLT3-ITD suggests that BEX1 expression is favorable for AML patients who are positive for the FLT3-ITD mutation." (PMID 26046670, 2015). "Of these genes, brain expressed X-linked protein 1 (BEX1), is known as candidate tumor suppressor gene and plays a role in cell cycle progression." (PMID 23236494, 2012). "Interesting findings include that SOX2 regulates the expression of SOX family proteins SOX1 and SOX18, and that SOX2 down regulates BEX1 (brain expressed X-linked 1) and BEX2 (brain expressed X-linked 2), two genes with tumor suppressor activity in GBM." (PMID 21211035, 2011). "We demonstrated by in vitro and in a xenograft mouse model that BEX1 or BEX2 possess tumor suppressor activity." (PMID 21211035, 2011). "BEX1 and FBLN were associated with ER, while FBLN1, HBEGF, KLK3, and TMPRSS2 were associated with tumor aggressiveness." (PMID 21134280, 2010). "In addition, we detected the protein level of five important genes and found that the expression of BEX1 in tumor cells and tissues was higher than that in normal liver cells and tissues." (PMID 37745297, 2023). "Compared with normal tissues, the expression levels of BEX1 in tumor tissues were significantly different, while the GCLM, G6PC, NEIL3 and NT5DC2 protein bands were unclear, which may be related to their low expression levels." (PMID 37745297, 2023). "Furthermore, we detected the protein level of five important genes and found that the expression of the other genes except BEX1 in tumor cells and tissues was higher than that in normal liver cells and tissues." (PMID 37745297, 2023). "Additionally, a role for Bex1 as a marker for hepatocyte differentiation/dedifferentiation processes and tumour formation was identified." (PMID 29907129, 2018). "The Bex1 transcript level has also been shown to be increased during hepatocyte dedifferentiation, and Bex1 is considered a marker for hepatocyte differentiation/dedifferentiation processes and tumour formation." (PMID 29907129, 2018).
tumor (continued). "The mechanism by which BEX1 displays its tumor suppressor activity might be cellular context dependent." (PMID 26046670, 2015). "Furthermore, re-expression of BEX1 resulted in a significant suppression of tumor growth and apoptosis induction in response to camptothecin treatment." (PMID 24626299, 2014). "It is possible that the expression level of BEX1 is tightly regulated, and either an overexpression or significant downregulation of BEX1 expression could lead to misregulation of BEX1 and drug resistance in the tumor cells." (PMID 24626299, 2014). "Thus, BEX1 appears to have different functions in different tumor types." (PMID 24626299, 2014). "Our volcano plot and GO analysis showed the significant downregulation of tumor-suppressive genes, such as ANOS1, CDH11, COL4A5, POSTN, PTN, and BEX1 in As- transformed cells, which is considered an early event of carcinogenesis." (PMID 35954277, 2022). "Another study found that the expression of BEX1 and BEX4 was upregulated in radiotherapy-resistant GBM cells and enhanced the tumor formation, growth, and radioresistance of GBM cells by activating the YAP/TAZ signaling pathway." (PMID 35860560, 2022). "BEX1- and BEX4-mediated YAP/TAZ activation enhanced the tumor formation, growth, and radioresistance of GBM cells." (PMID 34576008, 2021). "In ER-negative tumours, only MED7 (p < 0.00001), BEX1 (p = 0.032) and N-cadherin (p = 0.034) showed significant association with RXRG." (PMID 31558802, 2019). "Overexpression of BEX1 in mouse pro-B and myeloid cells resulted in decreased FLT3-ITD-dependent cell proliferation, colony and tumor formation, and in increased apoptosis in vitro and in vivo." (PMID 26046670, 2015). "BEX1, PTGDS, GRIK2 and WFDC1, also in the top 10 downregulated probesets, have all been identified as downregulated in tumours or as inhibitors of cell proliferation in immortalised cell lines." (PMID 24148222, 2013). "We have previously shown that BEX1 and BEX2 are silenced in GBM tumor specimens and exhibited extensive promoter hypermethylation." (PMID 21211035, 2011). "Since axon regeneration processes include the polymerization of microtubules and actin filaments, we hypothesized that alteration in cytoskeleton formation is mediated by BEX1 and BEX4 to accelerate cytoskeleton-mediated tumor progression." (PMID 34576008, 2021). "Our data suggested that SOX2 might down regulate BEX1 and BEX2 expression, reducing their tumor suppressor activities and thus promoting carcinogenesis." (PMID 21211035, 2011). "Because BEX1 expression reduced cell proliferation, inhibited colony formation and induced apoptosis, we aimed to check whether BEX1 expression delays FLT3-ITD-induced tumor formation in mice." (PMID 26046670, 2015).
cancer (12 papers, 2010 to 2023). A tumor composed of atypical neoplastic, often pleomorphic cells that invade other tissues. "A previous study has reported that brain-expressed X-linked protein 1 (BEX1) methylation mediated by DNMT1 inhibited HCC stemness and tumorigenicity, while DNMT1i ZEB promoted self-renewal and invasiveness in the high cancer stem cell (CSC) score HCC group." (PMID 36685594, 2022). "To figure out the potential roles of miR-5581-3p and BEX1 in cancer progression, we explored their expression in cancer tissues and cells." (PMID 33613672, 2021). "In contrast to our observations, Bex1 has been shown to have a pro-apoptotic role by binding to Bcl2 in cancer cells." (PMID 31827131, 2019). "According to the firebrowse database, the expression levels of BEX1 and BEX4 were considerably higher in GBM than in other types of cancers, suggesting that BEX1 and BEX4 may play an important role in GBM progression." (PMID 34576008, 2021). "Ingenuity analysis identified a group of 7 genes (BEX1, FBLN1, FGD3, HBEGF, KLK3, KLK6, and WNT5B) related to cancer, cellular function and maintenance, cellular growth, invasion, as well as proliferation with P < 0.001-0.05." (PMID 21134280, 2010). "BEX1 belongs to the BEX family and is found abnormally expressed in cancers." (PMID 33613672, 2021). "Expression of BEX1, BEX2, BEX4, and BEX5 were found to be reduced in different human cancers." (PMID 28083995, 2017). "The role of BEX1 in human cancer has not been thoroughly studied." (PMID 26046670, 2015).
cardiac disease (3 papers, 2017 to 2025). "BEX1 acts as an RNA-dependent mediator, stabilizing and enhancing the expression of pro-inflammatory mRNAs, thereby contributing to the progression of cardiac disease." (PMID 40526611, 2025).
infection (2 papers, 2022 to 2023). The state of being infected such as from the introduction of a foreign agent such as serum, vaccine, antigenic substance or organism. "On the other hand, the highest ranked down-regulated gene (in pattern IV) across all dpi was Bex2 (brain-expressed X-linked 2), while Bex1 and Bex4 trended similarly downward over the course of infection." (PMID 38107402, 2023). "Here we have identified the protein Brain Expressed X-Linked 1 (BEX1) as a novel antiviral protein that protects the heart from infection." (PMID 35192678, 2022). "We found that BEX1 KO MEFs are significantly more susceptible to infection by CVB3, as well as by influenza A virus (IAV) and Sendai virus ([SeV]; a murine parainfluenza virus)." (PMID 35192678, 2022). "We next sought to determine the physiological consequences of the loss of BEX1 during infection." (PMID 35192678, 2022). "As fibrosis is a hallmark of pathological cardiac remodeling post-infections, we utilized Masson’s trichrome staining to measure fibrosis and found that BEX1 KO hearts developed significantly more fibrotic tissue area by the fourth week of infection." (PMID 35192678, 2022). "In comparison to β-galactosidase-overexpressing controls, BEX1 overexpressing cardiomyocytes had reduced viral abundance 12 hours after infection." (PMID 35192678, 2022). "Despite equal viral load at day two post-infection, viral RNA levels were dramatically higher in BEX1 KO hearts than in WT hearts seven days after infection, suggesting that BEX1 is necessary to limit viral proliferation." (PMID 35192678, 2022). "The abundance of total leukocytes (CD45+) was significantly lower at seven days post-infection in the BEX1 KO hearts, suggesting that BEX1 KO mice have impaired immune cell recruitment." (PMID 35192678, 2022). "Conversely, overexpression of BEX1 confers protection from infection." (PMID 35192678, 2022). "However, cardiac ejection fraction was significantly lower in BEX1 KO mice than in WT mice at four weeks post-infection, suggesting the BEX1 KO hearts were more susceptible to virus-induced cardiac dysfunction." (PMID 35192678, 2022). "In this regards it is possible that BEX1 operates at multiple time points of infection, where its role on the immune system and the one directly affecting viral replication in the host could be uniquely important at different infectious disease stages." (PMID 35192678, 2022). "Additionally, we found that BEX1 KO cells had impaired production of IFN-β during infection, and addition of recombinant IFN-β could partially rescue the antiviral defect." (PMID 35192678, 2022). "Importantly, we saw that BEX1 restricts infection with multiple different viruses, which could suggest that BEX1 is a broad mediator of intrinsic cellular antiviral responses." (PMID 35192678, 2022). "No cardiac dysfunction was observed in either control or BEX1 transgenic mice at 28 days post-infection." (PMID 35192678, 2022).
BEX1 also shares sentences with these, for which no sentence is quoted: atrial fibrillation (1 paper); basal cell carcinoma (1); diabetic cardiomyopathy (1); epilepsy (1); hematological malignancies (1); idiopathic pulmonary arterial hypertension (1); infectious disease (1); Joubert syndrome (1); melanoma (1); metabolic syndrome (1); prostate carcinoma (1).